MMP9 (matrix metallopeptidase 9)
Diseases named in the same sentence as MMP9 in open-access papers (continued):
Sharing a sentence is not in itself a finding about the gene and the disease.
prostate carcinoma (continued). "The H2S donors Diallyl(di)sulfide also reduces MMP-2 and MMP-9 activities in human LNCaP prostate cancer cells and in an animal model of lung fibrosis." (PMID 27362269, 2016). "Other studies also consistently show that inhibition of MMP-2 and MMP-9 expression suppresses the metastatic potential of prostate cancer cells." (PMID 27340776, 2016). "TANs contribute to angiogenesis through matrix metalloproteinase 9 (MMP-9) in human fibrosarcoma and prostate cancer cells." (PMID 27169366, 2016). "We previously showed that HEGU and licoricidin reduce the invasion, adhesion, and migration of DU145 prostate cancer cells, as well as the secretion of MMP-9, ICAM-1, and VCAM-1." (PMID 27314329, 2016). "MMP-2 and MMP-9 expression levels are also used as biomarkers for prostate cancer malignant progression and therapeutic effects." (PMID 25402510, 2015). "In fact, elevated MMP9 secretion has been shown to result in decreased prostate cancer cell proliferation, coupled to increased sE-cadherin shedding." (PMID 25967040, 2015). "As exhibited in 5C, the protein expressions of c-Met, MMP1, MMP9 were decreased in siRNA transfected prostate cancer cells." (PMID 26337460, 2015). "MMP-2 and MMP-9 belong to a gelatinase group of MMPs and their role has been extensively studied in prostate cancer." (PMID 26052252, 2015). "MMP-9 and MMP-2 expression has been implicated in the development and progression of many tumors, such as bladder, colorectal, lung cancer and prostate cancer." (PMID 26742965, 2015). "The double S301A/S319A phosphorylation site mutation significantly reduces expression of VEGF, MMP9 and SPP1, migration and invasion of human prostate cancer cell lines and in vivo growth of tumor cell xenografts." (PMID 26204939, 2015). "Serum MMP-2 and MMP-9 levels were shown to be significantly increased in prostate cancer patients compared to controls." (PMID 24978435, 2014). "Androgen supplementation significantly reduced secretion and activity of MMP-9 in AR-positive prostate cancer cells grown in androgen-depleted media." (PMID 24978435, 2014). "Regulation: Tumor-stromal interactions regulate MMP-9 expression and their function in prostate cancer." (PMID 24978435, 2014). "The known transcriptional targets of Pea3 mostly include matrix metalloproteases, such as MMP-2 and MMP-9, identified in the context of breast or prostate cancer models." (PMID 25018694, 2014). "Altered MMP-9 expression on the cell surface and in its secreted forms is thought to contribute to enhancement of prostate cancer growth, metastasis and angiogenesis." (PMID 24978435, 2014). "Specifically, several cytokines and related proteins can regulate MMP-9 expression in prostate cancer." (PMID 24978435, 2014). "Interaction between angiogenic endothelial cells and prostate cancer cells has also been reported to activate an IL-6/androgen receptor/TGFβ/gelatinase B/MMP-9 signal pathway that augments prostate cancer invasion in association with angiogenesis." (PMID 24473089, 2014). "This utility has been highlighted by numerous works that have explored the expression of MMP-2 and MMP-9 in serum, urine, and tissues from prostate cancers." (PMID 25097794, 2014). "Western blot was used to examine the TIMP-1, TIMP-2, MMP-2 and MMP-9 expressions in prostate cancer cells." (PMID 24475196, 2014). "Fibroblast growth factor-inducible 14 (Fn14), a transmembrane receptor binding to TWEAK, promoted androgen-independent prostate cancer progression through MMP-9 and correlated with poor treatment outcome." (PMID 24978435, 2014). "It was shown that increased IL-6 expression, which is often seen in advanced prostate cancer, resulted in activation of MMP-9 expression through the TGF-β pathway." (PMID 24978435, 2014).
prostate carcinoma (continued). "LSD1 was also shown to act as a transcriptional activator during lytic replication of the herpes simplex virus, the expression of MMP-9 in retinal endothelial cells and the expression of vascular endothelial growth factor in prostate cancer cells." (PMID 24886859, 2014). "In a study conducted by Mukherjee and colleagues, the authors reported that treatment with EGCG resulted in the inhibition of cytokine and chemokine gene induction, cell migration, and activity of MMP-9 and -2 in prostate cancer." (PMID 25175005, 2014). "Thus MMP-2 and MMP-9 expression in the tissue and body fluids may be of diagnostic, prognostic and predictive value in the detection and/or clinical monitoring of disease progression and therapeutic efficacy in patients with prostate cancer." (PMID 24978435, 2014). "Studies showed that PDEF suppressed MMP-9 mRNA expression and resulted in decreased colony formation, cell migration, and cellular invasiveness in prostate cancer cells." (PMID 24978435, 2014). "Many studies indicate that increased levels of MMP-2 or MMP-9 in the serum or tissue samples of prostate cancer patients are correlated with advanced stage." (PMID 24475196, 2014). "Urinary MMP-9 activity was significantly higher in the urine samples from prostate cancer patients compared with controls." (PMID 24978435, 2014). "Co-culture of prostate cancer and stromal cells in vitro enhanced expression of pro-MMP-9 in prostate cancer cells, and down-regulated TIMPs in stromal cells." (PMID 24978435, 2014). "Bombesin, a neuropeptide hormone present in prostatic adenocarcinomas, stimulated secretion of MMP-9 in human prostate cancer cell lines." (PMID 24978435, 2014). "Recent reports suggest that IL-8 regulates the expression and activity of MMP-9 in human prostate carcinoma cell lines." (PMID 23349885, 2013). "In prostate cancer cells, silencing Id1 induced the expression of the cell cycle regulatory proteins p16 and p21 and triggered a change in MMP-9 levels." (PMID 23517130, 2013). "We previously reported that BK promotes cell migration of human prostate cancer cells through MMP-9 expression." (PMID 23803661, 2013). "We show here for the first time that MMP9 knockdown induces noninvasive cellular phenotype in prostate cancer cells." (PMID 23476138, 2013). "We have shown previously that OPN and αvβ3 signaling regulates the activity of MMP9 in prostate cancer PC3 cells." (PMID 24216994, 2013). "We reported previously that BK promotes migration of human prostate cancer cells through up-regulation of matrix metalloproteinase (MMP)-9." (PMID 23803661, 2013). "Results from the analysis indicated that expression levels of STAT3-regulated pro-angiogenic genes, such as S1PR1, MMP9 and HIF1a, correlated with the density of tumor-infiltrating B cells in human prostate cancers." (PMID 23734190, 2013). "To elucidate the possible roles of MMP9 in prostate cancer cell invasion/migration processes, we generated PC3 cells knockdown of MMP9 (PC3/Si)." (PMID 23476138, 2013). "In this first study we identify a possible role of miR-21 in the behavior of prostate cancer promoting a decay in the levels of RECK mRNA allowing the overexpression of MMP9." (PMID 22642976, 2012). "Certain result suggests that anti-invasive effect in androgen-independent prostate cancer by controlling MMP-9 expression through the suppression of the EGFR/JNK pathway." (PMID 22454661, 2012). "Overexpression of HMOX1 in prostate cancer cells downregulated the MMP9 expression and decreased the invasive potential." (PMID 22461839, 2012). "We found that high levels of EZH2 expression during cancer progression induce repression of TIMP genes (TIMP2 and TIMP3), leading to increased activity of MMP-9 and thus to increased invasive activity of prostate cancer cells." (PMID 22272343, 2012). "EZH2 knockdown markedly reduces the proteolytic activity of MMP-9, thereby decreasing the invasive activity of prostate cancer cells." (PMID 22272343, 2012).
prostate carcinoma (continued). "It is interesting to note that hypomethylation of the MMP-2 and MMP-9 genes increases gene expression and contributes to cancer cell invasiveness and tumourigenesis in malignant neoplasms, such as prostate cancer and lymphoma." (PMID 22866959, 2012). "C17orf37, whose expression correlates with grade and stage of nIBC, promotes invasion and migration of prostate cancer cells by enhancing secretion of uPA, MMP9 and VEGF through NF-kB pathway." (PMID 21339811, 2011). "Enhanced expression of MMPs has been correlated with increasing malignancy especially increased expression and activities of MMP-2 and MMP-9 are involved in the process of prostate cancer invasion and metastasis." (PMID 21219645, 2011). "In the future, it needs to be determined if MMP9 is critical for SLUG-induced invasion of prostate cancer cells." (PMID 22074556, 2011). "In human prostatic cancer cells, knock-down of Notch1 resulted in a downregulation of MMP9 and uPA and its receptor, uPAR." (PMID 21349159, 2011). "MT1-MMP, MMP-2 and MMP-9 are often overexpressed in advanced prostate cancers and play essential roles in prostate tumor metastasis." (PMID 21219645, 2011). "Next, we examined MMP9 activity in SLUG-overexpressing prostate cancer cell lines by gelatin-zymography." (PMID 22074556, 2011). "MT1-MMP and its substrates pro-MMP-2 and pro-MMP-9 are often overexpressed in a variety of cancers including prostate cancer and the expression levels correlate with the grade of malignancy in prostate cancer cells." (PMID 21219645, 2011). "Because MT1-MMP, MMP-2 and MMP-9 are all overexpressed in invasive prostate cancers, it is likely that increased activation of MT1-MMP/MMP-2 complex also activates proMMP-9 and acts as a major mediator of pericellular proteolysis." (PMID 21219645, 2011). "To address this question, we first examined MMP9 gene expression in prostate cancer cells that stably overexpress SLUG gene by qPCR and RT-PCR." (PMID 22074556, 2011). "In the present study, results revealed that PTEN silencing conferred CRC cells with an enhanced invasive capacity to migrate in vitro probably by inducing the expression of MMP-2, MMP-9 and uPA as it has already been observed in prostate cancer cells." (PMID 21203412, 2010). "It binds to plasminogen 2ε in the prostate cancer cell line 1-LN, triggering an intracellular [Ca2+] flux leading to the upregulation of MMP-9." (PMID 19654580, 2009). "CXCL12 and its receptor CXCR4 along with MMP-2 and MMP-9 are related with prostate cancer perineural invasion." (PMID 18983683, 2008). "The expression of CXCL12, CXCR4, MMP-2, and MMP-9 in human prostate cancer were higher than those in hyperplastic prostate tissues (P < 0.05)." (PMID 18983683, 2008). "Using the scid-hu model for bone metastasis, in which human prostate cancer cells are grown in human bone xenografts in scid mice 16, we confirmed high expression of mmp-2 and mmp-9 in cancer cells and in neighbouring bone stromal cells." (PMID 18769612, 2008). "The distribution and expression of CXCL12, CXCR4, MMP-2 and MMP-9 in human prostate cancer and in tumor cells invading nerve tissue were studied with immunohistochemical staining." (PMID 18983683, 2008). "Zoledronate as well as alendronate has been found to inhibit secretion and activity of MMP-2 and MMP-9 by tumor cells and tumor-infiltrating macrophages in mouse models of cervical cancer and prostate cancer." (PMID 18371232, 2008). "Alpha-methylacyl-CoA racemase, a phenotypic marker identified in the first microarray experiments on prostate cancer, was significantly over-expressed in cancer samples, as was MMP9." (PMID 18492237, 2008). "Taken together, these observations suggest that CD44 surface expression is an important event in the activation of MMP-9 and migration of prostate cancer cells." (PMID 17343740, 2007). "Quercetin inhibited EMT and down-regulated HIF-1α levels and MMP-9 in prostate cancer cell lines." (PMID 39859345, 2025).
prostate carcinoma (continued). "Targeted biomarker studies are needed to clarify whether MMP-9 is a modifiable mediator of ADT’s tissue remodeling effects—especially in prostate cancer progression, vascular injury, and cardiac remodeling." (PMID 41304763, 2025). "Moreover, we have previously reported that IRS-2 promotes MMP-9 secretion in the prostate cancer cell line PC3 and induces cancer cell overgrowth and malignant transformation." (PMID 39859555, 2025). "Additionally, Hibiscus sabdariffa leaf extract (HLE) effectively inhibited the activity and protein expression level of MMP-9 in human prostate cancer LNCaP cells in a concentration-dependent manner." (PMID 39683504, 2024). "Furthermore, immunohistology results of prostate cancer showed lower expression of AR and higher expression of MMP9 and FGF11." (PMID 36836690, 2023). "Furthermore, MMP9 expression was upregulated in cultured human prostate cancer cells including C4-2, C4-2B, LNCaP and CWR22Rv1 when co-cultured with mast cells." (PMID 36836690, 2023). "MMP-9 could play an important role in prostate cancer metastasis to bone through two mechanisms: the first mechanism acts on ECM and bone cell activity, while the second has a potential direct effect on the cancer cells themselves." (PMID 38138968, 2023). "MMP-9 levels were positively correlated with PSA levels in prostate cancer patients, which may indicate that this metalloproteinase is involved in bone metastasis." (PMID 38138968, 2023). "Most miRNAs participate in the regulation of the synthesis of a single MMP; however, miRNA-29b regulates MMP-2 synthesis in prostate cancer cells and MMP-9 expression in osteosarcoma, while miRNA-34a controls MMP-9 and MMP-14 production in tongue squamous cell carcinoma." (PMID 38069210, 2023). "Interestingly, the sonicated extract inhibited the migration of prostate cancer cells via the downregulation of MMP-9 and upregulation of TIMP-1." (PMID 36605288, 2022). "Additionally, PL inhibited the invasiveness and metastatic potential of prostate cancer cells by modulating the expressions of interleukin (IL)-6, IL-8, and MMP-9." (PMID 36046754, 2021). "In prostate cancer, NR2C2 could prevent or delay prostate tumorigenesis via regulating the ATM expression at the transcriptional level and could suppress prostate cancer invasion via altering the TIMP-1/MMP2/MMP9 signals." (PMID 34956884, 2021). "Next, the correlation between tpx2 with mmp3, mmp9 or ets-1 in prostate carcinoma was examined." (PMID 34123781, 2021). "In addition, FABP4 promotes tumor progression by altering the activities of matrix metalloproteinases (MMPs), especially MMP-2 and MMP-9, in prostate cancer." (PMID 34685761, 2021). "Furthermore, inhibition of GPC-1 decreased several markers of prostate cancer aggression, such as MMP-9, E-Cadherin (E-Cad), N-Cadherin (N-Cad), CXCR4, vimentin (VIM), Zeb1 and Zeb238–40, as determined using qRT-PCR." (PMID 31391540, 2019). "This hints that maintaining androgen concentrations may restrict MMP-9 expression and the invasive potential of prostate cancer epithelium." (PMID 31836808, 2019). "CXCL12/CXCR4 signalling activates MMP-9 expression in prostate cancer cells." (PMID 31718684, 2019). "Furthermore, the MMP-9 serum level was higher in chemoresistant prostate cancer patients upon disease progression." (PMID 30669448, 2019). "A previous study indicated that maspin blocked MMP9 expression in prostate carcinoma cells." (PMID 31861435, 2019). "AQP9 upregulation in prostate cancer could enhance growth, migration, and invasion involving ERK1/2 signaling; reduced levels of phosphorylated ERK1/2 and MMP9 were observed in AQP9-deficient cell lines." (PMID 29922644, 2018). "Moreover, S100A4 accelerates tumorigenesis and invasion of human prostate cancer by transcriptional regulation of MMP9." (PMID 30041429, 2018).
prostate carcinoma (continued). "However, we didn’t find any significant reduction in the secretion of active MMP9 after the treatment with Foxy-5 in either DU145 or PC3 prostate cancer cells." (PMID 28886116, 2017). "Furthermore, mesenchymal stem cells induced prostate cancer stem cell phenotype by promoting MMP-9 and snail expression and enhancing invasion." (PMID 29213108, 2017). "Hence, blockade of NF-κB was reported to inhibit in vitro and in vivo expression of vascular endothelial growth factor (VEGF), MMP-9 and interleukin-8 (IL-8) and consequently decreased neoplastic angiogenesis in human prostate cancer cells." (PMID 29118380, 2017). "Similarly, Cheng-Chung Li and his group found that a treatment with EPA and DHA decreased MMP9 level in prostate cancer cells." (PMID 26864323, 2016). "Knockdown of LCN2 suppresses the invasion of prostate cancer cells through downregulation of MMP-9." (PMID 26840566, 2016). "Our present study demonstrated that AQP9 regulates the expression of MMP9 in prostate cancer cells." (PMID 27187384, 2016). "It represses MMP-9 expression reducing cell migration in prostate cancer." (PMID 27124473, 2016). "MMP-26 has been shown to activate pro-MMP-9, thereby promoting invasion of prostate cancer cells." (PMID 27340776, 2016). "In addition, the ERK1/2/MMP9 pathway also reportedly modulates migration and invasion in colorectal cancer, prostate cancer and NSCLC by targeting various genes." (PMID 27777384, 2016). "Moreover, MMP9 appears to play a key role in promotion of invasion and metastasis in prostate cancer." (PMID 27187384, 2016). "For example, although elevated expression of MMP9 and MMP2 is a marker of poor prognosis in prostate cancer, and linked to metastasis, their expression is from tumor-associated stroma cells and not from the cancerous epithelial cells, where the gene repositioning was detected." (PMID 27507988, 2016). "Moreover, highly metastatic variants of prostate cancers are revealed to contain relatively high levels of MMP-2 and MMP-9." (PMID 25563361, 2015). "Silencing MMP9 in prostate cancer cells concomitantly inhibits ICAM-1 expression." (PMID 26513020, 2015). "Here, also consistent with our previous data, we report that OPNc-overexpressing cells induce Mmp2 and Mmp9 overexpression in ovarian carcinoma and prostate cancer cells, respectively, further corroborating a role of these gene products in activating cell invasion in both tumor models." (PMID 24928374, 2014). "Although there is a debate on increased prevalence of high-grade tumors among 5-ARI-treated patients, a recent study showed that finasteride may attenuate tumor aggressiveness and invasion through MMP-2 and MMP-9 downregulation in prostate cancer cells." (PMID 24978435, 2014). "In addition, in vitro studies also show that the expression of MMP-2 and MMP-9 promote invasion and lymph node metastasis of prostate cancer cells." (PMID 24475196, 2014). "There are discrepancies in reports of the expression of MMP-9 in prostate cancer tissue." (PMID 24978435, 2014). "It has been reported that NOTCH1 may regulate the expression of matrix metalloproteinase-9 (MMP9) in prostate cancer cells, which plays key roles in cancer invasion." (PMID 24621612, 2014). "Last but not least, it was shown that increased MMP-9 expression was associated with the loss of PDEF (prostate-derived ETS factor) in more aggressive prostate cancers." (PMID 24978435, 2014). "One report revealed the important roles of endothelial cells within the prostate cancer microenvironment to promote the prostate cancer metastasis and provide new potential targets of IL-6-- > AR-- > TGFbeta-- > MMP-9 signals to battle the prostate cancer metastasis." (PMID 24397471, 2014). "Induction of MMP9 activity may be a likely mechanism by which VEGF is released from prostate cancer." (PMID 24216994, 2013).